ERBB2 (erb-b2 receptor tyrosine kinase 2)
Diseases named in the same sentence as ERBB2 in open-access papers (continued):
Sharing a sentence is not in itself a finding about the gene and the disease.
tumor (continued). "During the past decades, the ERBB2 signaling cascade gained significant importance in the oncogenesis of many tumor types." (PMID 23630663, 2013). "In tumor cells, ErbB2 activates ErbB3 by stimulating several intracellular signaling proteins, such as MAPK, PI3K/Akt and Src kinase." (PMID 23739740, 2013). "Correlation analysis further revealed that tumor p-ezrin protein expression levels were positively correlated with increasing levels of the proto-oncogene receptor HER2/ErbB2." (PMID 24086451, 2013). "More specifically, knockdown of plakoglobin in MCF-7 cells resulted in the increased mRNA and protein levels of the tumor/metastasis promoters c-Abl, Snail, ErbB2 and MMP3 and the decreased levels of tumor/metastasis suppressors BRMS1, Kiss1 and Claudin-1." (PMID 24260116, 2013). "In COX-2MECKO mice transgenic for an activated ErbB2 mutant, wedetermined delayed tumor onset and reduced tumor multiplicity, as well as reduced tumorvascularization, compared to wild type (WT)." (PMID 24004819, 2013). "Nonetheless, the remaining tumor cells maintained a similar expression levels of both erbB2 and erbB3 receptors, which was consistent with the results of our cell culture studies." (PMID 24215614, 2013). "This short-term treatment led to a significant reduction in tumor incidence: by 3 months post ErbB2 activation, only three of the eight C188-9-treated mice had developed palpable tumors, while all 10 diluent-treated parous mice had done so." (PMID 24381245, 2013). "BT474 cells also carry physiologic levels of ErbB1 and ErbB3 and low levels of ErbB4, providing them a suitable model system for investigating the impact of ErbB signalling on tumour cell growth and ErbB2-targeted anti-tumour strategies." (PMID 23308242, 2013). "Without the treatment, tumors in both bim+/+ and bim−/− mice grew with MGR = 23.5%/day for bim+/+ and MGR = 12.0%/day for bim−/−, respectively, suggesting that BIM plays a role in ErbB2-mediated tumor growth." (PMID 23577147, 2013). "Given the importance of cytotoxicity in T cell function, we next sought to compare the ability of each CAR to lyse erbB2+ tumor cells." (PMID 23667569, 2013). "A large panel of tumor cell lines [referred to as neu ovalbumin peptide (NOP) lines] from spontaneous ErbB2/OVA-expressing mammary tumors were established." (PMID 23408142, 2013). "Specifically, although erlotinib is considered a specific EGFR inhibitor, it has been reported to inhibit other kinases including ErbB2 and Src family members in other tumor types." (PMID 24260133, 2013). "Each combination-inhibition (such as COX-2+EGFR and COX-2+ERBB2) presents a type of therapeutic perturbation for a tumor cell line." (PMID 23967306, 2013). "ErbB2/HER2 expression levels have been correlated with tumor size and lymph node metastasis, suggesting the involvement of ErbB2 and ErbB2-mediated signaling in tumorigenesis." (PMID 24204934, 2013). "EGFR and ERBB2 play important roles by dimerizing when their ligands binds to produce downward growth signals to the tumour cells." (PMID 23289484, 2013). "Frequently, upregulated gene expression of growth factor ligands and/or their receptors such as amplification and subsequent overexpression of ERBB2 or Hedgehog can contribute to tumor growth." (PMID 23760067, 2013). "In particular, immunostainings specifically revealed a decrease of cell surface ErbB2 in PyVT/HdhQ111/Q111 primary tumour cells upon Trastuzumab treatment." (PMID 23300147, 2013). "In the RKO tumor model we observed a significant decrease of ERBB2 in all the treatments with p values indicating stronger significance for the combination treatment." (PMID 23852390, 2013). "The therapeutic efficacy of trastuzumab relies both on its ability to elicit anti-tumor immunity by engaging FcR-mediated cytotoxicity and by blocking ErbB2-driven signal transduction." (PMID 23408142, 2013).
tumor (continued). "Perhaps upon aberrant stimulation with Wnt, these TOP-tva-expressing mammary cells, as well as other mammary cell subsets, can also become primed for tumor induction by ErbB2." (PMID 24265712, 2013). "We evaluated the levels of ErbB2 (rat neu or human HER2) in MMTV-PyVT/HdhQ7/Q7 and MMTV-PyVT/HdhQ111/Q111 tumours by immunohistochemistry and found a marked increase of ErbB2 in polyQ-expressing tumours as compared to the control tumours." (PMID 23300147, 2013). "The p16INK4a transgene dramatically delayed mammary tumorigenesis by ErbB2, indicating that ErbB2-mediated deregulation of cyclin D1/Cdk4/6 is a crucial step of tumor formation." (PMID 24205004, 2013). "We observed that EC1-GLuc-p53C not only targeted ErbB2 for bioluminescence imaging, but also selectively inhibited cell proliferation and tumor growth of BT474 in vitro and in vivo." (PMID 24069396, 2013). "We then analysed the levels of total and activated Akt – a well described downstream target of ErbB2 – in control and polyQ-huntingtin tumours." (PMID 23300147, 2013). "2D proliferation assays showed that in the absence of EGFR inhibition, lack of activation of the ERK1/2 pathway led to a strong decrease in cell growth while impairment of the AKT pathway reduced cell numbers less efficiently, except in ErbB2 tumor cells." (PMID 23028720, 2012). "Fifteen breast-tumor tissues in which ERBB2 amplification was determined either as ERBB2-positive or -negative with FISH were subject to the copy-number measurements." (PMID 23181561, 2012). "The cell lines different lineage, associated with the higher chromosomal instability revealed by HH-16.cl.4 (explaining the Erbb2 overexpression here observed), suggests different mechanisms involved in tumor progression of both cell lines." (PMID 22253826, 2012). "Recent studies have established that the ErbB2/ErbB3/PI3K complex forms the major oncogenic unit in ErbB2 amplified tumour cells, and that sebsequent activation of Akt is the major oncogenic mechanism." (PMID 23202898, 2012). "One of the main targets for Pyk2 is likely p130Cas, as it has been reported that p130Cas is essential for ErbB2 tumour progression." (PMID 22373082, 2012). "Taken together, these observations indicate that mammary epithelial disruption of FAK results in a dramatic reduction in ErbB2-induced tumours." (PMID 22373082, 2012). "First, we developed an IF protocol using the rabbit polyclonal antibody C-18, raised against the ErbB-2 carboxy (C)-terminal region, for the detection of ErbB-2 in paraffin-embedded tumor sections." (PMID 22356700, 2012). "Again these data suggest that retention of a functional FAK gene confers a strong proliferative advantage to ErbB2 tumour cells over their FAK-deleted counterparts." (PMID 22373082, 2012). "Most effort have concentrated on ErbB1 and ErbB2 owing to their increased expression in certain tumour cells relative to normal cells." (PMID 23202898, 2012). "We therefore chose the MCF-7 cell line as it represents the same tumour phenotype, that is, ER+, PR+, ERBB2−." (PMID 22134506, 2012). "For this purpose, we first evaluated a series of commercially available total and phospho-ErbB-2 antibodies for their capacity to detect protein expression and activation by IF in paraffin-embedded tumor sections." (PMID 22356700, 2012). "Anti-ErbB2 agents are increasingly used in the adjuvant setting after local regional treatment for a primary tumour." (PMID 23202898, 2012). "While a delay in tumour induction was noted, FAK-deficient tumours arose in 100% of female animals indicating that FAK is dispensable for ErbB2 tumour initiation." (PMID 22373082, 2012). "We examined PNMT-, NDUFC2-, and MTAP-associated outlying genes that were part of metabolic pathways and also ERBB2-, PAK1-, and CDKN2A-associated outlying genes that were related to the oncogenic/tumor suppressor pathways." (PMID 23383675, 2012).
tumor (continued). "The tumour-bearing FAKflx/flx mice developed lung metastases in the same proportion as the parental MMTV-activated ErbB2 strain with similar numbers of metastatic lesions." (PMID 22373082, 2012). "Whilst none of the three EGFR array peptides was found among phosphosubstrates distinguishing tumor KRAS/BRAF mutation status at group level, all of the three peptides representing ERBB2 and ERBB4 were among the discriminating substrates." (PMID 23226389, 2012). "Similar western blot analyses performed on serum-starved ErbB2 tumor cells showed basal phospho-EGFR, phospho-ERK1/2 and phospho-AKT levels that were abolished by AG1478 treatment." (PMID 23028720, 2012). "We found that in presence of this Met TKi, HGF lost its capacity to recover ErbB2 tumor cells from EGFR inactivation (A+P+H)." (PMID 23028720, 2012). "These lysates were compared with lysates from Neu/erbB2/HER1-induced mouse mammary tumors, where the erbB2 signaling pathway is the tumor driver." (PMID 22347416, 2012). "Taken together, these observations provide further evidence that retention of FAK signalling provides a profound proliferative advantage to ErbB2-driven tumour cells." (PMID 22373082, 2012). "It has been demonstrated that ERBB2 gene is overexpressed and unmethylated (in its promoter) in tumors and tumor cell lines, such as ovarian tumoral tissues and MCF-7 cell line." (PMID 22253826, 2012). "In our study, positive ERBB2 mRNA and protein expression was found in all established and short-term cultured OvCa cell lines tested as well as in fresh tumor cells derived from ascites or solid tumor utilizing RT-PCR, flow cytometry and western blot analyses." (PMID 23189165, 2012). "It is believed that such destabilization of client proteins (like raf, Src, Lck, Wee1, Mek, Cdk4, Src, Ck2, Akt, ErbB2 etc.)is responsible for the anti-mitotic and anti-tumor activity of the drug." (PMID 22361388, 2012). "Collectively these data indicate that FAK-ablated ErbB2 tumour cells are at a proliferative disadvantage relative to their FAK-expressing counterparts." (PMID 22373082, 2012). "The FAK-deleted ErbB2 tumour cells also showed impairment in migration, invasion and spreading compared to control cells." (PMID 22373082, 2012). "All primary uncultured tumor cells tested (n = 22) expressed ERBB2 mRNA at levels ranging from 35- to 1225-fold higher than CEM cells." (PMID 23189165, 2012). "Both MUC4 and ErbB2 are overexpressed in several epithelial cancers (pancreas, breast, lung, oesophagus, colon, ovary) and both have been shown to play roles in tumour development." (PMID 22393391, 2012). "The development of transgenic mouse models that recapitulate the initial events of ERBB2-induced mammary tumourigenesis has played a key role in understanding the molecular basis of ERBB2-driven tumours." (PMID 22621282, 2012). "To determine if the metastatic phase of ErbB2-induced tumour progression is affected by FAK deletion, we subjected the lungs from tumour-bearing mice to histological analyses." (PMID 22373082, 2012). "Reduction of ErbB2 expression previously shown in vitro by Western blotting was also confirmed in vivo in MUC4-KD tumours by IHC." (PMID 22393391, 2012). "Since lapatinib does not interact with the extracellular domain of ErbB2, it is able to inhibit trastuzumab resistant tumour cells that express p95 ErbB2." (PMID 23202898, 2012). "One of the most interesting findings of these studies was the observation that acute knockout of FAK from established ErbB2 tumour cells was more deleterious than early abrogation of FAK function in the MMTV-NIC model." (PMID 22373082, 2012). "Variables included in the Cox model were those which resulted statistically significant (p < 0.05) in the log rank test (nuclear ErbB-2 staining, N, age and tumor grade)." (PMID 22356700, 2012). "Trastuzumab inhibited glycolysis via downregulation of heat shock factor 1 (HSF1) and LDH-A in ErbB2-positive cancer cells, resulting in tumor growth inhibition." (PMID 22844340, 2012).
tumor (continued). "We will further discuss how regular alternative splicing events of these kinases are in some instances implicated in oncogenic processes during tumor progression (FGFR, TrkB, ErbB2, Abl, and AuroraA)." (PMID 22007291, 2012). "Activation of ErbB2/Neu kinase is also required for pro-invasive/metastatic activity in tumor cells, and we found that ErbB2 transcripts were significantly changed in Sema3E-positive OEC cells in gene profiling via RNA microarray analysis (data not shown)." (PMID 21559368, 2011). "The immune response elicited to human ErbB2 in rat ErbB2 transgenic mice is effective against tumor expressing human ErbB2, but poorly protective against those expressing the rat ErbB2 ortholog." (PMID 24212954, 2011). "Like many ErbB2-overexpressing tumours, the SK-BR-3 cell line has low levels of BRCA1 protein and mRNA." (PMID 21609478, 2011). "In biopsies from pelvic bone and liver metastases, immunohistochemical staining showed tumor cells negative (1+) for the erbB2 protein, but after the first three cycles of EOX, mainly positive erbB2 (3+) expressing tumor cells were seen in the bone marrow." (PMID 22014070, 2011). "An additionally study showed gene-specific quantitative PCR amplification of the erbB2 gene in tumor cells from lymph nodes and bone marrow from 98 patients with EC." (PMID 21481261, 2011). "Activation of the PI3K pathway can be achieved through a number of molecular mechanisms, including loss of the PTEN tumor suppressor gene, mutation in EGFR, and amplifications of ERBB2 (HER2NEU), as well as through mutation of PIK3CA." (PMID 21303542, 2011). "Here, 92 of 120 (76.7%) evaluated tumor cell nuclei scored positive with an average ERBB2/Centromere 17 ratio of 7,6." (PMID 22014070, 2011). "The best efficacy and positive therapeutic outcome with trastuzumab is observed in women with tumours that overexpress, have an amplification, or have high activity of ErbB-2." (PMID 21847123, 2011). "Induction of a specific and effective immune response to ErbB2 thus requires the circumvention of both central and peripheral, tumor-induced tolerance mechanisms." (PMID 24212954, 2011). "We used a meta-analysis based on seven data sets and found CEI1 was negatively correlated with ER/luminal-basal metagenes and ERBB2-molecular apocrine tumor metagenes; whereas CEI3 was positively correlated with the proliferation/AURKA metagene." (PMID 21798043, 2011). "ERBB2 and EGFR gene amplification were significantly associated with the depth of tumor invasion (P < 0.05) and lymph node metastasis (P < 0.05), but not with sex, age, or histological type (P > 0.05)." (PMID 21689422, 2011). "The gene analysis showed amplification of KRAS and ERBB2 oncogenes as possible molecular targets of therapy in tumor cells." (PMID 22014070, 2011). "In vitro, ERα+ lines such as MCF-7 and ZR-75-1, which were derived from ERα+/luminal A tumours, retain a molecular profile characteristic of luminal A tumours, including low expression of ERBB2; they also display poor invasive and metastatic ability." (PMID 22168360, 2011). "AP-2α is a central player in the positive regulation of ERBB2 expression, supported by studies demonstrating a correlation between AP-2α levels and expression of the receptor in tumour samples, but in conflict with other observations." (PMID 21375726, 2011). "Because p6.1 binds tumor cells bearing ErbB-2, it has potential as a tumor imaging agent or a vehicle for the specific delivery of radionuclide or cytotoxic agents to tumors overexpressing ErbB-2." (PMID 21258295, 2011). "We found ERBB2 membrane staining in the superficial cells of the normal bladder and ureter and in 72% of tumour tissues." (PMID 21364580, 2011). "How the role of AP-2α as a tumour suppressor reconciles with its activity in inducing ERBB2 is still unclear." (PMID 21375726, 2011).
tumor (continued). "Alterations in expression levels of genes, such as LOX, ATP5L, GALNT3, and MME revealed by large-scale sequencing were confirmed between cell lines as well as in tumor specimens with different ERBB2 backgrounds." (PMID 21731642, 2011). "Cell lines and tumours overexpressing ErbB2 have been reported to have particularly low BRCA1 levels." (PMID 21609478, 2011). "The immunoRNase was then characterised as an enzymatic protein, and tested for its biological actions in vitro and in vivo on ErbB2-positive tumour cells." (PMID 21559015, 2011). "Its antitumour activity has been also demonstrated in vivo on mice implanted with ErbB2-positive tumours." (PMID 21559015, 2011). "While EGFR is more highly expressed in eRMS tumor tissue ErbB2 expression is more prevalent in aRMS tumor tissue, and found in the majority of RMS tumors in the head and neck." (PMID 21253475, 2011). "There were two genes, in addition to HER2, clearly overexpressed in HER2+ tumours, GRB7 and MED24, which are both upstream of ERBB2 on chromosome 17 and previously associated with the HER2+ subtype." (PMID 22067903, 2011). "Application of IHC to evaluate the expression of ERBB2 in tumor cells has limitations, as the determination of staining is partially subjective, as opposed to strictly quantitative." (PMID 21689422, 2011). "In several of these mice, RHuT and HuRT elicited a stronger anti-tumor response than plasmids coding for fully human or fully rat ErbB2." (PMID 24212954, 2011). "Expression of ErbB2 is more prevalent in ARMS tumor tissue where it is found in the majority of RMS tumors of the head and neck." (PMID 21575221, 2011). "Using different mouse models, both groups concluded that STAT1 suppresses ERBB2/neu/HER2 tumor formation." (PMID 22185785, 2011). "We also examined inhibition of target activity by measuring EGFR and ErbB2 phosphorylation levels in tumor extracts at indicated times after a single administration of AST1306." (PMID 21789172, 2011). "ErbB2 is an attractive target for immunotherapy, as it is a transmembrane tyrosine kinase receptor, overexpressed on tumour cells of different origin, with a key role in the development of malignancy." (PMID 21559015, 2011). "In 50% of 17q12.21 gains, the erbB2 gene was gained in tumor cells from both lymph nodes and bone marrow." (PMID 21481261, 2011). "ErbB2 is an attractive target for immunotherapy, as it is a tyrosine kinase receptor overexpressed on tumour cells of different origin, with a key role in the development of malignancy." (PMID 21559015, 2011). "We also had previously shown that using a positive enrichment strategy for cells expressing both EpCam and ErbB2 antigens resulted in the detection of higher levels of tumour marker gene expression than enriching for cells expressing just one of the antigens." (PMID 21587256, 2011). "The CTC detection was performed using ErbB2/EpCAM immunomagnetic tumour cell enrichment followed by multimarker quantitative PCR (QPCR)." (PMID 21587256, 2011). "Most experimental studies are thus carried out on wild-type mice immunized against the rat ErbB2 and challenged with rat ErbB2+ mouse tumor cells." (PMID 24212954, 2011). "For ERBB2 analysis, 270 tumor cell nuclei were evaluated and 66 (24.4%) showed amplification with an average ERBB2/centromere 17 ratio of 6,1." (PMID 22014070, 2011). "For in vivo studies, Erb-hcAb-RNase was tested on murine TUBO tumour cells expressing ErbB2 of rat origin." (PMID 21559015, 2011). "To fill this gap in knowledge, in this study we analysed 10 primary USC cell lines for Her2/neu receptor expression and c-erbB2 gene amplification, and investigated Her2/neu ECD release in the supernatant of these biologically aggressive tumours." (PMID 21915118, 2011). "BT474 tumours excised were lysed and protein extracts were analysed by western blotting to detect tyrosine phosphorylated ErbB-2 (PY1248), total ErbB-2, phosphorylated ERK1/2, total ERK1/2, phosphorylated AKT1 and total AKT1 proteins." (PMID 21847123, 2011).